ADAM1A (ADAM metallopeptidase domain 1A (pseudogene))
Synonyms: ADAM1AP; FTNAP; PH-30a; Ftna; ADAM1P; formerly ADAM1
Gene: Unitary pseudogene on chromosome 12 (111,899,263 to 111,901,391, forward strand). Ensembl gene ENSG00000229186.
Diseases named in the same sentence as ADAM1A in open-access papers:
ADAM1A is named in the same sentence as 9 diseases in open-access papers, as found by Europe PMC text mining. Sharing a sentence is not in itself a finding about the gene and the disease. The quoted sentences say what the papers report.
Infertility (1 paper, 2022). "However, our results suggest that the decrease of Adam1a is not the main cause of C11orf94-null sperm infertility." (PMID 36050562, 2022).
ADAM1A also shares sentences with these, for which no sentence is quoted: tumor (2 papers); Alzheimer disease (1); amyloidosis (1); infection (1); iron deficiency (1); renal cell carcinoma (1); sperm (1); triple-negative breast carcinoma (1).